TRIM72 (tripartite motif containing 72)
Description:
Muscle-specific E3 ubiquitin-protein ligase that plays a central role in cell membrane repair by nucleating the assembly of the repair machinery at injury sites. Its ubiquitination activity is mediated by E2 ubiquitin-conjugating enzymes UBE2D1, UBE2D2 and UBE2D3 (By similarity). Acts as a sensor of oxidation: upon membrane damage, entry of extracellular oxidative environment results in disulfide bond formation and homooligomerization at the injury site (By similarity). This oligomerization acts as a nucleation site for recruitment of TRIM72-containing vesicles to the injury site, leading to membrane patch formation (By similarity). Probably acts upstream of the Ca(2+)-dependent membrane resealing process (By similarity). Required for transport of DYSF to sites of cell injury during repair patch formation (By similarity). Regulates membrane budding and exocytosis (By similarity).
Synonyms: Mg53
Tractability: Antibody: UniProt places it where antibodies can reach, with high confidence; its Gene Ontology location is reachable by antibodies, with medium confidence.
Gene: Protein-coding gene on chromosome 16 (31,214,119 to 31,231,537, forward strand). Ensembl gene ENSG00000177238.
Subcellular location: Cell membrane, sarcolemma; Cytoplasmic vesicle membrane
Subcellular location (Human Protein Atlas): Vesicles; Nucleoplasm
Pathways (Reactome):
Muscle contraction: Smooth Muscle Contraction
Gene Ontology:
Molecular function: identical protein binding; protein binding; phosphatidylserine binding; ubiquitin protein ligase activity; mitogen-activated protein kinase kinase kinase binding; ubiquitin conjugating enzyme binding; zinc ion binding
Biological process: innate immune response; muscle organ development; muscle system process; plasma membrane repair; proteasome-mediated ubiquitin-dependent protein catabolic process; protein homooligomerization; protein ubiquitination
Cellular component: cytoplasm; cytoplasmic vesicle membrane; sarcolemma
Genetic constraint (gnomAD): Loss-of-function variants: 34 observed, 27.56 expected, observed/expected ratio (o/e) 1.23, 90% interval 0.94 to 1.64. The synonymous counts are far from expectation, so gnomAD's model fits this gene poorly and the ratio says little. Missense variants: 664 observed, 523.12 expected, observed/expected ratio (o/e) 1.27, 90% interval 1.19 to 1.35. Synonymous variants: 299 observed, 236.75 expected, observed/expected ratio (o/e) 1.26, 90% interval 1.15 to 1.39.
Homologues: Orthologues: chimpanzee TRIM72 (100% identical), pig TRIM72 (94% identical), dog TRIM72 (92% identical), rabbit TRIM72 (92% identical), mouse Trim72 (91% identical), rat Trim72 (91% identical), guinea pig TRIM72 (90% identical), tropical clawed frog trim72 (58% identical). Paralogues in human: TRIM27 (27% identical), TRIM50 (27% identical), TRIM39 (27% identical), TRIM58 (26% identical), TRIM60 (26% identical), TRIM11 (26% identical), TRIM41 (26% identical), TRIM21 (25% identical), TRIM61 (25% identical), TRIM4 (25% identical), TRIM7 (24% identical), MID1 (24% identical), and 68 more.
Diseases named in the same sentence as TRIM72 in open-access papers:
TRIM72 is named in the same sentence as 86 diseases in open-access papers, as found by Europe PMC text mining. Sharing a sentence is not in itself a finding about the gene and the disease. The quoted sentences say what the papers report.
Insulin resistance (25 papers, 2013 to 2025). Increased resistance towards insulin, that is, diminished effectiveness of insulin in reducing blood glucose levels. "(2013) showed that TRIM72 acts as an E3 ligase targeting insulin receptor and insulin receptor substrate 1 for degradation, with abnormal TRIM72 expression causing insulin resistance and metabolic disorders." (PMID 33744959, 2021). "TRIM72/MG53 deficiency would alleviate insulin resistance and hyperlipidemia in HFD-mice, while TRIM72/MG53 overexpression would aggravate insulin resistance and hyperlipidemia." (PMID 37244925, 2023). "The muscle-specific E3 ligase Mitsugumin 53 (MG53, or TRIM72) is most abundantly expressed in the myocardium and its mutations are a primary causal factor of systemic insulin resistance and metabolic disorder." (PMID 35196979, 2022). "We aimed to investigate whether swimming exercise could improve insulin resistance (IR) by regulating tripartite motif family protein 72 (TRIM72) expression and AKT signal pathway in rats fed with high-fat diet." (PMID 27843952, 2016). "Recent work has pointed out a central role of the muscle-specific E3 ubiquitin ligase mitsugumin 53 (MG53; also called TRIM72) in promoting ubiquitin-dependent IR and IRS-1 degradation, which is associated with reduced IR signaling, insulin resistance, and metabolic disorders." (PMID 25566192, 2014). "SOCS1/3 and E3 ligase MG53 expression, also known as TRIM72, were elevated by inflammation and obesity, which may induce insulin resistance in adipose tissue, liver, and skeletal muscle." (PMID 26074875, 2015).
diabetes (19 papers, 2019 to 2025). "Our results align with previous studies in rodents indicating that TRIM72 is sufficient to promote diabetes through IRS1 downregulation, a finding supported by human data showing elevated TRIM72 and blood glucose following oral glucose administration." (PMID 41000062, 2025). "Trim72 has been reported as a potential therapeutic target in a variety of human diseases, such as type 2 diabetes mellitus, ischemic heart disease, drug-induced liver injury and severe burn injury." (PMID 39585917, 2024). "However, a contrasting role of TRIM72 in the regulation of diabetes has also been reported." (PMID 41000062, 2025). "This discrepancy may be explained by differences in experimental design, as TRIM72's negative effects on insulin signaling appear to be specific to models of severe diabetes where it exacerbates, rather than initiates, metabolic dysfunction." (PMID 41000062, 2025). "This discrepancy may be explained by differences in experimental design, as TRIM72's negative effects on insulin signaling appear to be specific to models of severe diabetes." (PMID 41000062, 2025).
muscular dystrophy (14 papers, 2012 to 2025). Muscular dystrophy (MD) refers to a group of more than 30 genetic diseases characterized by progressive weakness and degeneration of the skeletal muscles that control movement. "These membrane repair proteins have been shown to contribute to human disease; disruption of the TRIM72/MG53, caveolin-3, and dysferlin complex, as well as mutations in the dysferlin and caveolin-3 genes, can result in muscular dystrophies." (PMID 35563723, 2022). "The TRIM family protein TRIM72 has been shown to be an essential component of the cellular membrane repair in muscles, with evidence supporting some positive effects in mouse models of muscular dystrophy." (PMID 36352383, 2022). "TRIM72/MG53 has also been linked with multiple pathologies, including muscular dystrophies." (PMID 35563723, 2022).
Obesity (14 papers, 2013 to 2026). Accumulation of substantial excess body fat. "Thus, Trim72 could be a useful therapeutic target in obesity, IR, and T2DM because insulin sensitivity and glucose uptake is highly increased in the enhanced skeletal muscle." (PMID 23326526, 2013).
myocardial infarction (10 papers, 2020 to 2025). Gross necrosis of the myocardium, as a result of interruption of the blood supply to the area, as in coronary thrombosis. "MG53, a protein encoded by the TRIM72 gene, is predominantly expressed in mouse skeletal and heart muscle and has been shown to protect cardiomyocytes from injury and reduce the size of myocardial infarction in animal models." (PMID 37477774, 2023).
diabetic cardiomyopathy (6 papers, 2019 to 2024). Diabetic cardiomyopathy is a disorder of the heart muscle in people with diabetes. "Tumor necrosis factor receptor superfamily member 12a (Tnfrsf12a) and tripartite motif containing 72 (TRIM72) overexpression have been associated with atherosclerosis and diabetic cardiomyopathy, respectively." (PMID 31625260, 2020).
Sepsis (6 papers, 2020 to 2024). Sepsis is defined as life-threatening organ dysfunction caused by a dysregulated host response to infection. "Moreover, recent researches revealed an additional anti-inflammatory role of TRIM72 concerning chronic tissue injury, sepsis, or viral infection." (PMID 36713032, 2023).
acute kidney injury (5 papers, 2017 to 2024). Sudden and sustained deterioration of the kidney function characterized by decreased glomerular filtration rate, increased serum creatinine or oliguria. "Given that the kidney is a primary site of C. albicans infiltration in mice leading to abscess formation and renal failure, the increased mortality in Trim72-/- mice was probably due to the increased evidence of kidney damage and decreased clearance of C. albicans from the kidney." (PMID 39585917, 2024).
lung carcinoma (5 papers, 2020 to 2026). "The high expression of tripartite motif containing 72 (TRIM72) in patients with pCR is consistent with findings from lung cancer, where it was shown to inhibit cellular proliferation and tumor progression, and to enhance sensitivity to cisplatin." (PMID 41541656, 2026). "Chen and colleagues showed that knockout of TRIM72/MG53 through CRISPR-gene silencing led to aggressive lung tumor growth and metastasis in mice, raising the possibility that MG53 might possess tumor suppressor function in lung cancer 31-33." (PMID 36147477, 2022). "Knockout of TRIM72/MG53 through CRISPR-gene silencing led to aggressive lung tumor growth and metastasis in mice, raising the possibility that MG53 might possess tumor suppressor function in lung cancer." (PMID 34521423, 2021). "We show that MG53, a member of the TRIM protein family (TRIM72), modulates G3BP2 activity to control lung cancer progression." (PMID 34521423, 2021). "After 6 weeks, enriched sgRNA sequencing was performed in mice with lung cancer metastasis, and several candidate genes related to lung metastasis were identified and verified, including the already known genes PTEN241, miR-345,242 and miR-152243 and several new genes, including Fga, Trim72 and Nf2." (PMID 32296011, 2020).
myocardial ischemia (5 papers, 2020 to 2025). A disorder of cardiac function caused by insufficient blood flow to the muscle tissue of the heart. "The endogenous ADP-ribosylated TRIM72 level was elevated in Arh1-deficient mice following cardiac ischemia-reperfusion injury." (PMID 32092898, 2020). "Additional evidence suggests that serum TRIM72 is released from injured or dead cells and is detectable following muscle injury induced by cardiac ischemia-reperfusion and treadmill exercise." (PMID 32092898, 2020).
Skeletal myopathy (5 papers, 2019 to 2024). "TRIM72/MG53 is an essential component of the membrane repair machinery as TRIM72/MG53 ablation results in defective membrane repair, progressive skeletal myopathy, and vulnerability to ischemia-reperfusion injury." (PMID 32271817, 2020).
colon carcinoma (3 papers, 2021 to 2024). "has demonstrated that low immunohistochemical expression of TRIM72 could predict relapse in stage II colon carcinoma." (PMID 35004288, 2021).
Duchenne muscular dystrophy (2 papers, 2021 to 2025). Duchenne muscular dystrophy (DMD) is a neuromuscular disease characterized by rapidly progressive muscle weakness and wasting due to degeneration of skeletal, smooth and cardiac muscle. "Trim72 deletion in skeletal muscles worsens the pathological features of Duchenne muscular dystrophy (DMD), leading to greater muscle fragility and degeneration over time." (PMID 40998017, 2025).
fibrosis (2 papers, 2023). the formation of excess fibrous connective tissue in an organ or tissue in a reparative or reactive process. "Tripartite motif protein 72 (TRIM72), a protein containing a tripartite motif, can regulate cardiac fibrosis by targeting fibroblast proliferation and transition to myofibroblast." (PMID 37593048, 2023).
lung fibrosis (2 papers, 2020 to 2024). "In vivo data revealed a cell/tissue-protective and anti-fibrosis effect of TRIM72 in injury-induced lung fibrosis model." (PMID 32471489, 2020). "In this study, we tested the membrane reparative role of TRIM72 in ATII cells and the role of TRIM72 in injury-induced lung fibrosis using an intratracheal bleomycin (bleo) injection (i.t.)model." (PMID 32471489, 2020). "To further examine if TRIM72-mediated epithelial protection leads to reduced lung fibrosis, we assessed fibrotic markers in bleo-treated lungs at day 14 after bleo exposure." (PMID 32471489, 2020). "In vivo studies demonstrated that TRIM72 protects the integrity of the alveolar epithelial layer and reduces lung fibrosis." (PMID 32471489, 2020). "Additionally, our study provides the first evidence of Trim72’s role in regulating P300 ubiquitination, which may suggest a novel mechanism for the Trim72-mediated modulation of pulmonary fibrosis." (PMID 38671868, 2024). "In this study, we tested the specific roles of TRIM72 in the repair of ATII cells and the development of lung fibrosis." (PMID 32471489, 2020).
renal fibrosis (2 papers, 2022 to 2024). A final common manifestation of a wide variety of chronic kidney diseases characterized by glomerulosclerosis and tubulointerstitial fibrosis. "Prior reports have shown that TRIM family proteins play an important role in kidney fibrotic disease, TRIM72, TRIM6 and TRIM18 were involved in the development of renal fibrosis by regulating downstream inflammatory pathways." (PMID 38195664, 2024).
tongue cancer (2 papers, 2021 to 2023). A malignant neoplasm affecting the tongue. "TRIM72 was also revealed to inhibit tumor progression in tongue cancer by regulating PI3K-AKT signaling pathway." (PMID 35004288, 2021).
Candida infection (1 paper, 2024). "First, the source of Trim72 and the factors regulating Trim72 secretion during Candida infection is unclear." (PMID 39585917, 2024). "To investigate the expression of Trim72 during C. albicans infection, we established a systemic candidiasis model by intravenous injection of C. albicans." (PMID 39585917, 2024). "Numerous studies have demonstrated that Trim72 can be detected in striated muscle, alveolar epithelial cells and renal proximal tubular epithelium cells and secreted into the blood circulation, suggesting that these cells may be the potential cellular origin of Trim72 during Candida infection." (PMID 39585917, 2024). "In summary, we demonstrated the protective role of Trim72 in antifungal responses by recruiting macrophages via enhancing cell migration capacity and upregulating CCL2 producing through NF-kB and ERK1/2 signaling during Candida infection." (PMID 39585917, 2024).
Candidemia (1 paper, 2024). A form of invasive candidiasis where species of CANDIDA are present in the blood. "To test the relevance of our findings in mice to humans, we collected serum to test Trim72 concentrations from 37 patients with candidemia and 20 healthy volunteers." (PMID 39585917, 2024). "On day of first blood culture positivity for C. albicans, serum Trim72 concentrations were significantly elevated in candidemia patients versus healthy controls, and survivors of candidemia patients had significantly higher serum Trim72 levels than non-survivors." (PMID 39585917, 2024). "Our study further showed that serum Trim72 were significantly elevated in candidemia patients compared to healthy controls on day of first blood culture positivity for C. albicans, and that survivors of candidemia patients had significantly higher serum Trim72 levels than non-survivors." (PMID 39585917, 2024).
chronic kidney disease (1 paper, 2024). Impairment of the renal function secondary to chronic kidney damage persisting for three or more months. "TRIM72 and autophagy and beclin 1 regulator 1 (AMBRA1) levels have been shown to be significantly low in patients with chronic kidney disease (CKD)." (PMID 38225560, 2024).
fungal infection (1 paper, 2024). "Here, we report that Trim72 positively regulates antifungal immunity during lethal fungal infection." (PMID 39585917, 2024). "This study may provide a theoretical basis for the treatment of fungal infections by targeting Trim72." (PMID 39585917, 2024). "Therefore, the effects of Trim72 on mouse macrophages can be partially extended to human macrophages, supporting a clinical and translational role of Trim72 in treating humans with fungal infection." (PMID 39585917, 2024). "Here we demonstrate that Trim72 may protect against fungal infection by enhancing macrophage recruitment through NF-κB and ERK1/2 signaling-mediated increased cell migration and CCL2 generation in macrophages." (PMID 39585917, 2024). "Trim72 has potential therapeutic effect in a variety of human diseases, however the role of Trim72 in fungal infections is completely unknown." (PMID 39585917, 2024). "However, the role of Trim72 in the pathogenesis of fungal infections is completely unknown." (PMID 39585917, 2024).
invasive candidiasis (1 paper, 2024). "Whereas recombinant Trim72 protein treatment protects mice against invasive candidiasis." (PMID 39585917, 2024).
neuroblastoma (1 paper, 2024). Neuroblastoma (NB) is the most common solid, extracranial childhood tumor. "Then mRNA level and protein level of TRIM72 were also analyzed in N2a cells (mouse neuroblastoma cell line) and SK-N-SH cells (human neuroblastoma cell line)." (PMID 38408103, 2024).
tumor (11 papers, 2019 to 2026). "The identification of the LINC01852/TRIM72/SRSF5/PKM2 signaling axis provides new insights into the molecular mechanisms underlying drug resistance and tumor progression, identifying new therapeutic targets for CRC." (PMID 38263157, 2024). "Some reports demonstrated that TRIM72 could act as a tumor suppressor in cancer." (PMID 35004288, 2021). "Mechanistically, LINC01852 functioned as a molecular scaffold to enhance the interaction of TRIM72 with SRSF5 and facilitate TRIM72-mediated degradation of SRSF5, thus inhibiting aerobic glycolysis, tumor growth and chemoresistance." (PMID 38263157, 2024).
cancer (9 papers, 2019 to 2024). A tumor composed of atypical neoplastic, often pleomorphic cells that invade other tissues. "This study demonstrated that LINC01852 acts as a molecular scaffold to facilitate the interaction between SRSF5 and TRIM72, promoting TRIM72-mediated degradation of SRSF5, and these findings reveal a novel lncRNA-based mechanism that regulates SRSF5 expression and function in cancer cells." (PMID 38263157, 2024).
cardiovascular diseases (5 papers, 2019 to 2024). "Low expression of TRIM72 was responsible for development of cardiovascular diseases, but loss of this gene may be linked with progression of CAD." (PMID 31881747, 2019). "Trim72 is a striated muscle-specific tripartite motif (TRIM) family protein that plays a dual role in the occurrence and development of cardiovascular diseases." (PMID 35997993, 2023).